ZEB1 (zinc finger E-box binding homeobox 1)
Diseases named in the same sentence as ZEB1 in open-access papers (continued):
Sharing a sentence is not in itself a finding about the gene and the disease.
gastric cancer (continued). "A role for HULC in the regulation of EMT has been observed in HCC where it functions as a ceRNA for miRNAs (miR-122, miR-200a-3p, miR-372, and miR-488) to mediate EMT via upregulation of Snail, ZEB1, or ADAM9, and this lncRNA has also been reported to induce EMT in gastric cancer." (PMID 29701689, 2018). "To address the molecular mechanisms by which Brg1 contributes to gastric cancer cell migration and tumor metastasis, we examined a series of well-characterized EMT regulators such as Snail, ZEB-1, Twist-1 and β-catenin in AGS in a doxycycline (DOX)-based Brg1 inducible system." (PMID 30177679, 2018). "Furthermore, by conducting secondary analyses we confirmed both ZEB1 and ZEB2 played important roles in gastric cancer prediction." (PMID 28416756, 2017). "In the present study, it was observed that IGF-I induced EMT and upregulated ZEB2, but not ZEB1, Twist1 or Twist2, in gastric cancer BGC-823 cells." (PMID 25435948, 2015). "Further, continuous exposure to the low-oxygen environment could also be a contributing factor in ZEB1 and ZEB2 upregulation in gastric cancer." (PMID 25197668, 2014). "Without indisulam, DCAF15 could significantly downregulate ZEB1 in HCC cells while DCAF15 could hardly regulate ZEB1 in gastric cancer cells." (PMID 36805336, 2023). "Similarly, our current experiments showed that neither overexpression nor knockdown of DCAF15 altered the ZEB1 protein level or inhibited the migration of gastric cancer cells." (PMID 36805336, 2023). "Moreover, we also detected decreased expression of E-cadherin and increased expression of N-cadherin, Snail, Slug and Zeb1 in both cell lines after coculture with BMDMs, which implies that TAMs may activate EMT of gastric cancer cells." (PMID 36797541, 2023). "Since our previous work revealed that RBM39 mediated the indisulam-inhibited proliferation and this work demonstrated the role of ZEB1 in the regulation of indisulam-inhibited migration of gastric cancer cells, we did not explore the function of RBM39 on indisulam-regulated migration." (PMID 36805336, 2023). "In addition to PDGF-D, PDGF-B not only contributes to EMT in gastric cancer cells by activating MAPK/ERK pathway, but also promotes the expression of zinc finger E-box binding homeobox 1 (ZEB1) by downregulating the expression of miR-200 in triple negative breast cancer." (PMID 35659308, 2022). "Neutrophils in the stroma of gastric cancer (GC) produce IL17a and CXCL5 both promoting EMT, indicated by upregulation of VIM and ZEB1, whereas CDH1 is repressed." (PMID 34459003, 2021). "The effect of NOX-enhanced tumor metastasis in gastric cancer could be mediated through regulation of EMT markers, including MMPs, fibronectin, vimentin, snail, zeb1, and E-cadherin 62, which is consistent with our findings that MMP expression was essential for NOX4-regulated CRC cell invasion." (PMID 32641980, 2020). "Moreover, previous studies have found that miRNA-101 inhibits the cell proliferation and augmented apoptosis in gastric cancer, colon cancer and NSCLC by targeting zinc finger E-box binding homeobox 1 (ZEB1), cyclooxygenase-2 (Cox-2), enhancer of zeste homologue 2 (EZH2) and Mcl-1." (PMID 32212793, 2020). "However, after ZEB1 knockdown, further knockdown of DCAF15 did not alter the effect of indisulam on the migration of gastric cancer cells." (PMID 36805336, 2023). "To explore whether H. pylori infection depended on ZEB1 to induce PRTG expression, we firstly detected the expression of ZEB1 in H. pylori-infected and non-infected gastric cancer tissues." (PMID 33542225, 2021). "Owing to the lack of suitable blockers target to ZEB1/PRTG axis, the development of more specific and pharmacologically tractable antagonists that block PKG1α activity could provide novel approaches to improve gastric cancer outcomes." (PMID 33542225, 2021).
colon carcinoma (112 papers, 2011 to 2026). "Coincidently, miR-21-5p was positively associated with the expression of NGF, p-ERK, p-ELK1, and ZEB1 in human colon cancer tissues." (PMID 36522730, 2022). "Reports have shown that ZNF185 and ZEB1 expression are significantly associated with liver metastasis and are independent indicators of liver metastasis and prognosis in colon cancer patients." (PMID 36358661, 2022). "Accordingly, Wnt ‘super-activation’ by GSK3β inhibition (i.e., Chiron) in the APC/CTNNB1-mutated colon cancer cell lines results in a significant expansion of EpCAMlo cells and increased ZEB1 expression." (PMID 34036938, 2021). "We next focused directly on β-catenin, since it has been reported as necessary for SOX17 transcription of FOXA1 and associated with regulating the transcription factor ZEB-1 by the tight junction protein Claudin-1 in colon cancer cells." (PMID 33669586, 2021). "ZEB1 expression underlies in vivo the establishment and maintenance of the subpopulation of EpCAMlo colon cancer cells, thereby contributing to increased dissemination along the invasion-metastasis cascade." (PMID 34036938, 2021). "PRNP expression is highly associated with the EMT signature in colon cancer patients, and PrPC is known to control the expression of ZEB1 in colon cancer cells." (PMID 33276687, 2020). "The β-catenin/TCF4 complex induces the epithelial-to-mesenchymal transition (EMT)-activator ZEB1 to promote tumor invasion in APC-mutated colon cancer." (PMID 27007150, 2016). "In colon cancer, ZEB1 was expressed at the invasive front of tumors, in association with the transient loss of basement membranes." (PMID 23844063, 2013). "The importance of Zeb1 in IL-1β-induced EMT in colon cancer cells is further highlighted in Zeb1 knockdown HCT-116 cells, which display a close association between the lack of EMT and the disappearance of IL-1β-induced repression of E-cadherin transcription in these cells." (PMID 23174018, 2012). "Indeed, IL-1β treatment led to EMT of colon cancer cells with loss of E-cadherin, up-regulation of Zeb1, and gain of the mesenchymal phenotype." (PMID 23174018, 2012). "Overall, these findings suggest that ZEB1 in fibroblasts regulates colon cancer initiation and progression in a tumor context- and stage-dependent manner." (PMID 38937629, 2024). "NGF derived from has been shown to activate the TrkA/ERK/ELK1/ZEB1 signaling pathway in colon cancer cells." (PMID 38816365, 2024). "In a previous study, it has been shown that rIL-1β promotes EMT and stemness through ZEB1 activation, and increases drug resistance in colon cancer cells." (PMID 39451241, 2024). "As a central EMT regulator, ZEB1 is overexpressed in various cancer types including lung, breast and colon cancer and plays a critical role in EMT and tumorigenicity." (PMID 36936987, 2023). "Meanwhile, the Schwann cells-derived NGF activated TrkA/ERK/ELK1/ZEB1 signaling pathway in colon cancer cells, which further enhanced the expression of exosomal miR-21-5p." (PMID 36522730, 2022). "The effect of the GM-CSF on the MAPK/ERK/ZEB1 pathway has been reported in colon cancer, but the detailed mechanism remains unexplored." (PMID 36329016, 2022). "In sum, we confirmed a switch in isoform expression (CD44v6 vs. CD44s and NUMB1/3 vs. NUMB2/4) as a function of ESRP1 and ZEB1 expression in colon cancer." (PMID 36346211, 2022). "In summary, our data demonstrated that NGF increased ZEB1 expression in colon cancer cells through TrkA/ERK/ELK1." (PMID 36522730, 2022). "The chi-square test identified that miR-21-5p was positively correlated with NGF, p-ERK, p-ELK1, and ZEB1 in the colon cancer specimens." (PMID 36522730, 2022). "As previously reported, the EpCAMlo subpopulation of colon cancer cells is earmarked by increased expression of the ZEB1 transcription factor, responsible for EMT activation and for their quasi-mesenchymal and highly metastatic phenotype." (PMID 36346211, 2022).
colon carcinoma (continued). "The correlation in the expression between NGF and ZEB1 was determined by Pearson’s correlation, and ZEB1 was found to be positively correlated with NGF in colon cancer tissues from our cohort and the TCGA cohort." (PMID 36522730, 2022). "DCLK1 contributes to the promotion of EMT by means of the overexpression of mesenchymal markers (Vimentin) and transcriptional regulators (ZEB1) and the downregulation of the epithelial marker E-cadherin in colon cancer cells." (PMID 35717205, 2022). "Coincidentally, the data showed that both the intracellular and exosomal expression of miR-21-5p in colon cancer cells was significantly increased or decreased upon ZEB1 overexpression or knockdown, respectively." (PMID 36522730, 2022). "We analyzed the invasive front of a small cohort of colon carcinomas by IHC with antibodies directed against β-catenin and ZEB1 in consecutive sections." (PMID 34036938, 2021). "The consistent presence of cells with nuclear co-localization of ZEB1 and β-catenin located at the invasive front of patient-derived colon carcinomas validates these observations." (PMID 34036938, 2021). "The co-culture of colon tumor organoids with this population of CAFs resulted in the upregulation of vimentin and ZEB1 in tumor cells." (PMID 34680267, 2021). "In colon cancer, Daxx downregulation decreases E-cadherin expression via Zeb1-mediated transcriptional inhibition, leading to increased metastasis." (PMID 34359912, 2021). "In colon cancer, vitamin D up-regulates KDM6B and causes the expression of ZEB1, ZEB2, SNAI and other metastasis-related genes." (PMID 34001062, 2021). "Given the concordant transcript abundance of Snail and Zeb1, we next examined the miR-34a and miR-200 abundance in colon cancer samples." (PMID 34502497, 2021). "Overall, the results highlight the key role played by enhanced Wnt signaling activation in establishing and maintaining the EpCAMlo subpopulation of colon cancer cells through ZEB1 upregulation and EMT induction." (PMID 34036938, 2021). "Immunohistochemical analysis of MYC, Cortactin, and ZEB1 also showed AXT suppresses metastasis of colon cancer cells into lung." (PMID 31263239, 2019). "We found that colon cancer patients with increased Zeb1 expression showed reduced DFS with significant difference (p < 0.05)." (PMID 30979372, 2019). "Taken together, these findings clearly indicate that AXT suppresses ZEB1 by the restoration of miR-200a level, and influences the invasive capability of colon cancer cells." (PMID 31263239, 2019). "Qin and colleagues reported that TERT promotes EMT in colon cancer through the Zinc finger E-box binding homeobox 1 (ZEB1) pathway." (PMID 31200515, 2019). "Kaplan–Meier analysis of survival between colon cancer patients with increased ZEB1 and decreased CDH1 expression vs. patients with low ZEB1 and high CDH1 values promotes the possible prognosis value for the combination between the two genes." (PMID 29352232, 2018). "The statistical analysis showed that RHBDD1 and ZEB1 exhibited a moderately positive correlation in 71 colon cancer tissues (Spearman r: 0.5312, P < 0.0001)." (PMID 29426364, 2018). "We additionally proved the positive correlation between RHBDD1 and ZEB1 at the protein level in primary colon cancer samples from patients." (PMID 29426364, 2018). "In summary, the present study demonstrated the important role of miR-205 alone in suppression of EMT and restoration of the epithelial phenotype of in vitro colon cancer cells through ZEB1 targeting and CDH1 upregulation." (PMID 29352232, 2018). "Survival curves based on ZEB1/CDH1 expression sustained the important role of the two genes in colon cancer prognosis, where combination between increased ZEB1 expression and decreased CDH1 levels significantly reduced the time of survival." (PMID 29352232, 2018).
colon carcinoma (continued). "Third, we finally analyzed the expression of transcription factors known to be mediators of EMT in colon cancer cells, namely ZEB1, SNAI1 (also known as Snail), SNAI2 (also known as Slug), and TWIST." (PMID 29462209, 2018). "Based on the previous direct association of miR-205-5p and ZEB1, RT-qPCR analysis on HCT-116 colon cancer cells exhibit a decrease in mRNA levels compared with the control counterparts 48 h after miR-205-5p (10 nM) exogenous upregulation." (PMID 29352232, 2018). "Clinically, RHBDD1 expression was positively correlated with ZEB1 at the protein level in 71 colon tumor tissues." (PMID 29426364, 2018). "In summary, nesfatin-1/NUCB-2 enhanced migration, invasion and EMT in colon cancer cells through LKB1/AMPK/TORC1/ZEB1 pathways in vitro and in vivo." (PMID 27150059, 2016). "The IL-32θ-induced inhibition of STAT3 results in the downregulation of ZEB1, Bmi1 and also upregulation of E-cadherin signaling in colon cancer cells." (PMID 26824417, 2016). "In this study, the authors unravel an additional role for H2A.X in the regulation of mesenchymal-like traits and activation of the EMT transcription factors, Slug and ZEB1, in colon cancer cells." (PMID 26876487, 2016). "Zeb1 also downregulates the polarity factor lethal giant larvae 2 (Lgl2) in colon cancer cell lines and promotes colon cancer cell metastasis." (PMID 21324165, 2011). "Similarly, SCs-derived NGF activates TrkA/ERK/ELK1/ZEB1 signalling in colon cancer cells inducing the expression of mesenchymal markers such as vimentin, N-cadherin and Zeb1 and promoting tumour invasiveness and metastasis formation." (PMID 40037534, 2025). "ZEB1 mediated IL‐1β expression and promoted colon cancer cell stemness and invasiveness." (PMID 37192201, 2023). "Similarly, exosomal miR-200c-3p suppresses the migration and invasion of lipopolysaccharide (LPS)-treated colon cancer cells by targeting zinc finger E-box-binding homeobox-1 (ZEB-1)." (PMID 36612314, 2023). "Moreover, ZEB1 can promote colon cancer invasion by regulating the molecules involved in matrix remodeling, such as uPA and plasminogen activator inhibitor-1 (PAI-1)." (PMID 36358661, 2022). "Moreover, knockdown of ZEB1 suppressed the upregulation in the intracellular and exosomal levels of miR-21-5p in colon cancer cells when co-cultured with Schwann cells." (PMID 36522730, 2022). "Therefore, the mRNA expressions of EMT factors (E-cad, N-cad, Snail, Slug, Twist, Zeb1, and MMPs) were analyzed using the gene expression profile data of TCGA colon cancer." (PMID 36076991, 2022). "Moreover, Schwann cells boosted the expression of miR-21-5p in colon cancer cells by upregulating ZEB1." (PMID 36522730, 2022). "Thus, Schwann cells increased miR-21-5p expression in colon cancer cells by regulating ZEB1 expression." (PMID 36522730, 2022). "In the present study, we found that circCSPP1 promoted EMT in colon cancer by modulating ZEB1." (PMID 35101080, 2022). "IL-1β fosters the epithelial to mesenchymal transition (EMT) process and stem cell proliferation in human primary colon cancer cells and in HCT-116 cells through the zinc finger E-box-binding homeobox 1 (ZEB1) protein, which contributes to the advancement of colon tumors." (PMID 35954156, 2022). "Furthermore, ZEB1 expression was decreased upon the knockdown of ELK1 in colon cancer cells, both at mRNA and protein levels." (PMID 36522730, 2022). "NGF promotes ZEB1 expression in colon cancer cells through secretion of NGF." (PMID 36522730, 2022). "E-cadherin expression was reduced by Claudin-1 via upregulating of ZEB-1 in colon cancer cells." (PMID 35280730, 2022). "Additionally, ZEB1 not only promotes the migration of tumor cells in pancreatic and colon cancer, but also serves essential roles on the initiation of tumor." (PMID 34796112, 2021).
colon carcinoma (continued). "VB significantly inhibits tumor cell metastasis and invasion by inhibiting Rac-1, hypoxia inducible factor-1α (HIF-1α), and Zeb-1 signaling pathways, which may be the most metastatic phenotype of colon cancer-suitable drug candidates." (PMID 33768139, 2021). "Of note, ZEB1 plays many pleiotropic roles ranging from the modulation of oncogenic and tumor-suppressive pathways, cell-fate determination, stemness, and cell plasticity and is as such likely to be a determinant in colon cancer invasion and metastasis." (PMID 34036938, 2021). "Our experimental results are consistent with the results obtained in some previous studies, indicating that P2 × 7 receptor can regulate the expression of MMP-2, E-cadherin, N-cadherin, Vimentin, Zeb1, and Snail, and affect the invasion and migration of colon cancer cells." (PMID 33330466, 2020). "In their 2015 study using HCT116 and SW480 colon cancer cell lines, the Yang lab found that by physically interacting with the transcriptional repressor zinc finger E box-binding homeobox 1 (ZEB1), TERT downregulates the expression of E-cadherin, a tumor suppressor whose loss-of-function drives EMT." (PMID 32599885, 2020). "Overexpression of miR-200a inhibited the mRNA and protein level of ZEB1 in colon cancer cells." (PMID 31263239, 2019). "Furthermore, the upregulation of E-cad and the downregulation of zinc-finger E-box binding homeobox 1 (ZEB1) and N-cadherin (N-cad) can significantly inhibit metastasis and invasion of colon cancer cells." (PMID 31772677, 2019). "Similarly, colon cancer patients with increased Zeb1 expression showed significantly (p < 0.05) reduced OS compared with patients with the low levels." (PMID 30979372, 2019). "Given that ZEB1 promotes the stemness and invasiveness of pancreatic and colon cancer cells via activation of EMT45,46, our results indicated that the tumorigenic role of ISL1 may be achieved, at least partially, through activation of ZEB1 in GC." (PMID 30674889, 2019). "Mechanistic studies demonstrated that Nrf2-mediated PSMD4 expression may promote more than just colony formation, cell invasion, and soft agar growth, and may also confer 5-FU resistance in colon cancer cells via the NF-κB/AKT/β-catenin/ZEB1 cascade." (PMID 29899863, 2018). "In conclusion, DDX3 may play an oncogenic role to promote tumor growth and invasion in colon cancer cells via the β-catenin/ZEB1 axis due to increasing KRAS transcription." (PMID 27007150, 2016). "In colon cancer cells, HIF-1α directly binds to a hypoxia response element (HRE) in the proximal promoter of ZEB1 causing an increase in the transactivation and expression of ZEB1." (PMID 27706047, 2016). "STAT3 can induce EMT of colon cancer cells, activate ZEB1 and suppress E-cadherin." (PMID 26824417, 2016). "In addition, we demonstrated nesfatin-1/NUCB-2 enhanced migration, invasion and mesenchymal phenotype in colon cancer through LKB1/AMPK/TORC1/ZEB1 pathways." (PMID 27150059, 2016). "In colon carcinomas, high levels of Zeb1 and CtBP were correlated with low levels of E-cadherin." (PMID 25301737, 2014). "Interestingly, genes that are associated with colon cancer progression (ANTXR1, EFEMP2, SULF1, TAGLN, VCAN, ZEB1 and ZEB2) were upregulated in patients co-overexpressing TAZ-AXL-CTGF." (PMID 23372686, 2013). "In addition, ZEB1 interacts via its N-terminal region with BRG1 to repress E-cadherin in colon cancer cells." (PMID 24216980, 2013). "Thus, IL-1β and Zeb1 can be potential therapeutic targets aimed at cancer stem cells in the development of novel treatments for colon cancer." (PMID 23174018, 2012). "Furthermore, ZNF248 was found to bind to ZEB1 in two colon cancer cells using IP assays." (PMID 39247604, 2024). "Thus, we speculated that Schwann cells might promote miR-21-5p expression in colon cancer through ZEB1." (PMID 36522730, 2022).